CD4 (CD4 molecule)
Diseases named in the same sentence as CD4 in open-access papers (continued):
Sharing a sentence is not in itself a finding about the gene and the disease.
influenza (continued). "Experimental studies of T-cell-mediated response in mice have demonstrated that influenza-specific memory CD8+ and CD4+ cells are sufficient to protect against heterosubtypic influenza challenge." (PMID 29631629, 2018). "For initiating CD4+ T cell and CD8+ T cell responses following influenza vaccination adjuvanted with TLR ligands, direct sensing of pathogen-associated molecular patterns (PAMPs) by DCs is a crucial step." (PMID 29649134, 2018). "Overall, these data are consistent with the priming of CD4 T cells with diverse functional potential and for selection of a subset of these virus-specific CD4 T cells, enriched for IFN-γ potential for traffic to the lung after influenza infection." (PMID 29681900, 2018). "Live-attenuated influenza vaccines, on the other hand, are capable of limited replication in cells, more effectively stimulating CD8 as well as CD4 T cells and antibody." (PMID 29666412, 2018). "The percentage of active caspase-3-positive cells, as well as the median fluorescence intensity (MFI) of active caspase-3 staining, were increased in the CD44high population of both CD4+ and CD8+ T cells after Flu infection, compared to the CD44low population." (PMID 29352186, 2018). "Similar studies in mice have confirmed CD4+ and CD8+ T cell cross-reactivity with pandemic and “pre-pandemic” influenza strains, and further established their ability to confer protection." (PMID 29666412, 2018). "Previously it has been shown that C3 deficiency results in enhanced viral spread and impaired recruitment of virus-specific CD4+ and CD8+ effector T cells in the lung during seasonal influenza infection owing to attenuated T cell priming." (PMID 28301559, 2017). "In fact, during influenza virus infection, influenza-specific cytotoxic activity of CD8 CTLs is impaired in the chronic phase of infection, and CD4 CTLs can function instead." (PMID 28280496, 2017). "After vaccination with an unadjuvanted 2009 pandemic H1N1 monovalent influenza vaccine, HAI titers were also significantly increased in women with higher CD4+ T-lymphocyte counts." (PMID 28883971, 2017). "Because there were a limited number of cells remaining available from these timepoints and H1N1 CD4 epitopes overlapped with those of other recently circulating influenza strains, we used HAI antibody titers as a proxy for CD4+ T-cell responses." (PMID 28193244, 2017). "The capacity of influenza-infected DCs from aged individuals to prime CD4+and CD8+ effector T cells is also significantly reduced, as compared to influenza-infected DCs from young individuals." (PMID 28587289, 2017). "While both CD4+ and CD8+ T cells can contribute to protection against influenza, CD8+ T cells are particularly beneficial when they recognize conserved epitopes across multiple influenza strains." (PMID 27602032, 2016). "We recently demonstrated that H1-specific CD4+ Th1 cells and cytotoxic CD8+ T cells also played a role in the protection against a heterologous influenza strain." (PMID 27525409, 2016). "Several studies have shown that CD4+ T memory cells contribute to an effective defence against specific viral pathogens (e.g. RSV and influenza)." (PMID 27793198, 2016). "The licensed intranasal live influenza vaccine induces systemic and mucosal cross-reactive CD8+ and CD4+ T-cells." (PMID 27242800, 2016). "The role of CD4 cells in protection against influenza is less well characterized than CD8, but recent studies have shown a correlation between CD4 T cell responses and protection in a human influenza challenge study." (PMID 27602032, 2016). "In the context of influenza infection, the co-stimulatory molecule CD40 has a role in helping both the CD4+ and CD8+ T cell responses." (PMID 26910342, 2016). "CD4+ Th and CD8+ CTLs are important in protection from infection by different viruses, including influenza, HIV, HPV, and the Epstein–Barr virus." (PMID 27752254, 2016).
influenza (continued). "CD4CD8 double-positive cells in pigs are activated memory CD4 cells, meaning S-FLU appears capable of inducing both CD4 and CD8 memory, both of which have been shown to be important in protective immunity to influenza." (PMID 27183611, 2016). "Specifically, we found that CD4 T cell-directed TGF-β was a critical signal for anti-viral Tfh differentiation, GC B cell reactions, and isotype-switched antibody response during influenza infection." (PMID 25569154, 2015). "After influenza vaccination, healthy volunteers showed a significant increase in the frequency of H1N1-specific IL-4+CD4+ T cells after vaccination." (PMID 26641243, 2015). "This MHC-II restricted epitope was discovered in humans exposed to 2009 strains of swine-origin influenza (H1N1) and induces strong CD4 T cell responses." (PMID 26270649, 2015). "Use of the VH1-69 germline gene is associated with cross-reactive hemagglutinin (HA) stem-binding mAbs against influenza, the influenza HA receptor binding domain, HIV-1 CD4 induced epitopes, hepatitis C virus, and others." (PMID 26226263, 2015). "The T cell immune response is characterized by expansion of naive CD4 and CD8 cells into effector T cells specific for some influenza viral proteins." (PMID 24696530, 2014). "FACS analysis revealed rapid induction of ICOS expression on CD4+ and CD8+ T cells early after influenza infection." (PMID 25029240, 2014). "As CD4 CTL have been shown to be important in influenza, HIV and anti-tumor responses, this information will be vital for inducing potent CD4 effectors with multifunctional properties against a variety of diseases." (PMID 24586481, 2014). "We conclude that day 14 γδT cells behaved similarly to short-term activated γδT cells in their ability to process simple (influenza M1) and complex (PPD) antigens and to induce antigen-specific CD8+ and CD4+ αβT cell responses." (PMID 25101086, 2014). "Again, both groups of DCs were able to induce a comparable CD4 and CD8 T cell IFNγ response to influenza (p = 0.250 and p = 0.822 respectively)." (PMID 25475068, 2014). "Intranasal immunization of mice with hemagglutinin and neuraminidase from influenza strain PR8 resulted in enhanced IgA and CD4+ T cells." (PMID 26344621, 2014). "The association of protection with CD4+ T cell responses is in agreement with recent clinical data demonstrating that pre-existing CD4+ T cells responding to conserved influenza proteins, including NP, correlate with protection, even in the absence of influenza antibodies." (PMID 24523886, 2014). "NP-expressing vectors induced high numbers of influenza-specific CD4+ and CD8+ T cells and high titer influenza-specific antibody responses." (PMID 24523886, 2014). "Following intranasal influenza infection, NKG2A−/− mice display decreased frequency of CD8+ T cells but show similar frequencies of CD4+ and NP366 -specific CD8+ T cells the BAL when compared to C57BL/6 (WT) mice." (PMID 25251060, 2014). "However, CD4 T cells may also play an important role in immunity to influenza." (PMID 24788814, 2014). "In the present study, we demonstrated that CHS induced the presence of CD4+CD25+Foxp3+ Tregs, and this correlated with the downregulation of both Th1 and Th2 immune response stimulated by H5N1 influenza vaccination in mice." (PMID 24151582, 2013). "BAL cells and PBMCs from carriage negative volunteers were stimulated with pneumococcal antigens (HK-6B or 6B c/s) or influenza and cytokine (TNF, IL-17A or IFNγ) producing CD4+ memory T-cells were subsequently detected by ICS and flow cytometry." (PMID 23555269, 2013). "Previous studies suggest that effector CD4+ and CD8+ T cell-mediated immune responses contribute to protection from influenza." (PMID 24349390, 2013). "One of the aims of this study was to investigate the capacity of the test vaccines to induce CD4+ and CD8+ T cell responses in the different study cohorts, as these cells are known to be important in providing protection against influenza infection." (PMID 24066003, 2013).
influenza (continued). "For example, IFN-α and IFN-β produced by pDC have been shown to increase CD69 expression and IFN-γ production from CD4+ T cells, and also activate CD8+ T cells upon influenza challenge." (PMID 23815813, 2013). "Infection of DR1 mice with influenza PR8 generated a response that was comparable to that in B10 mice, with predominantly IFN-γ-secreting CD4 T cells and greater numbers of IgG2c than IgG1 antibody-secreting cells." (PMID 22457834, 2012). "In the present study, we utilised a model of recombinant influenza expressing a single, Leishmania-specific LACK158–173 (Leishmania homologue of receptors for activated C kinase) CD4+ T cell peptide." (PMID 22470440, 2012). "Both CD4+ and CD8+ T cell sets play an important role in influenza-specific T cell-mediated immunity." (PMID 23230439, 2012). "We observed that vaccination with influenza subunit vaccine and imiquimod resulted in a higher frequency of IFN-γ+ effector CD4+ T cells compared to mice immunized with subunit vaccine alone." (PMID 22848514, 2012). "The influenza-specific proliferative CD4+ T-cell responses in HIV-infected patients were similar between those that had a CD4 count>350 and those with a CD4 count<350 (0.76%[0.1–3.2] vs. 1.44%[0.5–2.9]; p>0.05)." (PMID 22715399, 2012). "A significant influenza-driven recall response was generated in pigs vaccinated with the adjuvanted split vaccine in the CD4+CD8−, CD4+CD8+ and CD4−CD8+ subsets (4±1%, 16±4% and 12±1% CFSElow cells, respectively, P<0.05, n = 3)." (PMID 22427834, 2012). "Contrary to our expectations we observed comparable pneumococcal, influenza and MTB-PPD CD4 T-cells in both the mucosa and circulation of Malawian adults, showing no distinct compartmentalization of immune responses to URT pathogens." (PMID 23284694, 2012). "The comparable proportions of IL-4- and IFN-γ-secretors among the virus-specific CD4 T cells in DR1 mice was surprising and inconsistent with the Th1-polarized response expected after influenza infection." (PMID 22457834, 2012). "In general, donors 65 and older showed a reduced frequency of influenza reactive T cells following ex vivo stimulation with influenza virus (P = 0.054 for CD8 T cells and P = 0.005 in the CD4 populations)." (PMID 21887299, 2011). "To determine whether the reduced population of EM CD4 T cells in ICOS−/− mice was associated with reduced protection to re-infection, we infected Balb/c and ICOS−/− mice with the influenza virus Hkx31, rested the mice for over 30 days, then challenged with the more lethal strain of influenza, PR8." (PMID 21364749, 2011). "We found a higher proportion of the influenza responsive CD8 and CD4 T cells were of this late effector CD45RA+ phenotype, and that CD8 but not CD4 T cells had also significantly lost expression of costimulatory molecules CD28 and CD27." (PMID 21887299, 2011). "Although most data come from cell lines and CD4+ T cell clones, it has been shown that CD4+ T cells specific for LCMV, influenza have cytotoxic activity in vivo." (PMID 21943070, 2011). "Our results further showed that specifically blocking Dll1 during influenza infection impaired the survival and inflammatory status in our model with a decreased number of IFN-γ+CD4+ and IFN-γ+CD8+ T cells." (PMID 22072963, 2011). "Blockage of Dll1 resulted in accelerated inflammatory responses and decreased IFN-γ levels from CD4+ and CD8+ T cells during influenza infection." (PMID 22072963, 2011). "In the lungs, a rapid increase of HA-specific CD4- and CD8 T cells was observed in vaccinated mice shortly after challenge with influenza swine flu virus, which probably contributes to the strong inhibition of pulmonary viral replication observed." (PMID 20808939, 2010). "To extend our observations into a system that would enable us to simultaneously investigate the contribution of antigen presentation by different DC subsets to both CD4+ and CD8+ T cells, we utilized influenza infection in BALB/c mice." (PMID 18301768, 2008).
influenza (continued). "Smoke exposed mice had greater numbers of both CD4+ and CD8+ cells that stained more intensely for CD25, particularly with influenza infection." (PMID 18627612, 2008). "Second, CD4+ and CD8+ T lymphocytes play a major role in the immune responses to respiratory virus infections (ex influenza and parainfluenza viruses)." (PMID 18335041, 2008). "Smoke and influenza mice had fewer CD3+ CD4+ (helper T) lymphocytes and CD3+ CD8+ (cytotoxic T lymphocytes) in their LNs, at both d3 and d10, than influenza alone mice." (PMID 18627612, 2008). "Both CD4+ and CD8+ T cells produce IFN-γ, and smoke reduced the number of these cells in LNs of influenza infected mice at both d3 and d10, while smoke and influenza mice had very high numbers of both types of T cells in BALF at d10." (PMID 18627612, 2008). "Another recent study demonstrates that intranasal vaccination with a commercial influenza vaccine adjuvanted with NexaVant (NVT), a TLR3 agonist, effectively boosts lung CD4+ TRM cells, which are key to cross-protective, long-lasting immunity against diverse influenza strains." (PMID 40407543, 2025). "The necessity of such CD4+ T cell help is demonstrated in attenuated primary CD8+ T cell responses against vaccinia virus, influenza, herpes simplex virus, and in vaccination with Ad‐vectored vaccines in the absence of CD4+ T cells." (PMID 39604225, 2025). "In individuals aged 60 years and older, both humoral (HI) and cellular (CD4+ T cells) responses were stronger in those receiving adjuvanted influenza vaccines compared to those receiving non-adjuvanted, standard-dose vaccines." (PMID 41012125, 2025). "The observed decline in the CD4/CD8 ratio and reduction in memory B cells in pregnant women with influenza infection suggest weakened cellular and humoral immune defenses, potentially rendering pregnant women more vulnerable to influenza, particularly during the middle and late stages of pregnancy." (PMID 40558593, 2025). "Furthermore, the R-DOTAP was reported to stimulate more durable CD4+ and CD8+ T cells with poly-function than AddaVax, and, these T cell receptors (TCRs) also recognized more distinct influenza peptides." (PMID 39982912, 2025). "The crucial role of CD4+ T cells in the expansion of memory CD8+ T cells and effective secondary responses is evident in models of influenza, Ad‐vectored vaccines, and critically even when such help was dispensable for the primary response, such as LCMV and L. monocytogenes infection." (PMID 39604225, 2025). "CD8+ T cells, for example, during influenza infection without CD4+ T cell help are metabolically dysfunctional and exhibit an exhausted phenotype." (PMID 40857407, 2025). "BLIMP1 is known to be essential for CD8+ T cell differentiation and cytotoxic function during influenza infection; however, the effect of BLIMP1 deficiency on CD4+ T cell responses in influenza infection has not been reported." (PMID 40680114, 2025). "At a low dose (0.01 μg), a sa‐mRNA encoding HA and NA antigens from H5N1, H3N2, H1N1 and Yamagata influenza strains elicited robust neutralising antibodies and CD4+ and CD8+ T‐cell responses in mice and protected ferrets from influenza at a 0.5 μg dose, with undetectable viral loads." (PMID 40853332, 2025). "More importantly, preexisting CD4+, but not CD8+, T cells responding to influenza internal proteins were associated with lower virus shedding and less severe illness." (PMID 40279312, 2025). "Based on these observations, we performed the same analysis using T cell frequencies measured in BAL, which again revealed that influenza-specific CD4 + T cells, but not CD8 + T cells, correlated with survival following challenge with HPAI." (PMID 39030218, 2024). "CD4+ T cells recognize viral peptide fragments presented on major histocompatibility complex class-II (MHC-II) molecules and play a crucial role in enhancing CD8+ T cell and B cell responses during influenza infection." (PMID 38892370, 2024).
influenza (continued). "Additionally, tissue-resident memory (TRM) CD4+ and CD8+ T cells, which persist in lung tissue, have been shown to enhance protective immune responses during influenza infection." (PMID 39772053, 2024). "In this study we used heterologous priming with adjuvanted rGP intramuscular immunization or LCMV intranasal infection to generate memory CD4+ T cells and investigate the effects of recalled memory CD4+ Tfh cells and established TRM cells on the response to influenza challenge." (PMID 39283916, 2024). "Furthermore, there is growing interest in the significance of CD4+ and CD8+ T cell responses following influenza infection and vaccination." (PMID 39340066, 2024). "However, heterologous infection or immunization priming of CD4+ T cells drove a significant increase in the number of total Fas+GL7+ GC B cells and influenza HA-specific GC B cells at 8 dpi." (PMID 39283916, 2024). "Assessment of the T cell response from influenza-stimulated organoids did not reveal any significant differences in the total frequencies or phenotypes of CD4 and CD8 T cells between males and females (data ​​not shown)." (PMID 38812520, 2024). "Cell-mediated immune (CMI) responses, in particular the stimulation of CD4+ and CD8+ T-cells, could also contribute to the protection against influenza infection." (PMID 39772052, 2024). "For example, mice lacking CD40 or CD4+ T cells resulted in detectable levels of influenza-specific IgG after influenza virus infection, providing a similar level of protection against influenza virus re-infection comparable to that of WT mice." (PMID 39772016, 2024). "In addition, heterologous infection or immunization priming generated an increased long-lived CD4+ TRM pool and induced increased expansion of recalled antigen-specific CD4+ T cells in the lung after influenza challenge." (PMID 39283916, 2024). "In contrast, influenza vaccination in patients receiving PD-1 blockade displayed a more robust follicular helper CD4 T cell response compared to patients without treatment." (PMID 39257577, 2024). "In line with previous observations of CMV vaccine vectors in nonhuman primates, high frequencies of transgene-specific CD4+ and CD8 + T cells were observed in the BAL at the final timepoint measured prior to influenza challenge in both FL and dd CyCMV/Flu-vaccinated MCM (bottom row)." (PMID 39030218, 2024). "As the CD4+ T cell-specific immunodominant LCMVgp61-80 epitope contains a cryptic epitope recognized by CD8+ T cells, we analyzed CD8+CD44+ T cells at 8 and 42 days after influenza challenge for IFNγ expression following LCMVgp61-80 peptide restimulation." (PMID 39283916, 2024). "Antigen-specific CD8+ T cells that are cross-reactive between heterosubtypic influenza infections can restrict the influenza challenge, resulting in the lack of a boosted CD4 T cell response to the secondary challenge." (PMID 39283916, 2024). "Regardless of MHC-restriction, both CD8+ and CD4 + T cells from CyCMV/Flu-vaccinated MCM recognized a panel of diverse influenza isolates in vitro." (PMID 39030218, 2024). "Thus far, post‐vaccination changes in numbers of circulating follicular (CXCR5+) CD4+ T cells and plasmablasts (CD19 + CD27 + CD38+) at day 7 were described as some of the best correlates of antibody responses to influenza vaccination." (PMID 38146131, 2024). "This fact underpins the feasibility of the development of new vaccination strategies for the elderly using vaccines based on CD4+ CTL NP epitopes, as it is well known that with age, the number of CD4+ CTLs increases, but the activity of these cells upon influenza vaccination remains unchanged." (PMID 38140152, 2023). "In the influenza infection model, CD4 T-cell depletion has no impact on the expansion and migration of memory CD8+ T cells into the lung parenchyma, but it does impair the expression of CD103 and CD69 on these cells in the tissue." (PMID 37545498, 2023).